IFI6 (interferon alpha inducible protein 6)
Diseases named in the same sentence as IFI6 in open-access papers (continued):
Sharing a sentence is not in itself a finding about the gene and the disease.
pancreatic cancer (2 papers, 2021). "Overall, these results indicated that IFI6 is a crucial target for the lncRNA CTD-3252C9.4 to exert biological roles in pancreatic cancer." (PMID 34399768, 2021). "Taken together, we discovered that down-regulation of CTD-3252C9.4 facilitates pancreatic cancer progression via unbinding IRF1 to amplify IFI6 expression, hindering cell apoptosis and facilitating cell proliferation." (PMID 34399768, 2021). "By binding to IRF1 to abolish its transcriptional activity, CTD-3252C9.4 inhibits the transcription of IFI6, which then leads to the activation of apoptosis signaling pathway in pancreatic cancer cells." (PMID 34399768, 2021). "By binding to the transcriptional factor interferon regulatory factor 1 (IRF1), CTD-3252C9.4 prevents the transcription of IFI6, which ultimately induces pancreatic cancer cell apoptosis and represses cell survival." (PMID 34399768, 2021). "KLF7 promotes pancreatic cancer growth and metastasis by upregulating ISGs that include IFI6, interferon-induced protein with tetratricopeptide repeats 1 (IFIT1) and IFIT328." (PMID 34650128, 2021). "Since anti-apoptosis plays a crucial role for tumor development and the functional role of IFI6 in pancreatic cancer has not been clarified as yet, we focused predominantly on the effects of CTD-3252C9.4 targeting IFI6 on pancreatic cancer cell apoptosis and survival." (PMID 34399768, 2021). "Nevertheless, either the biological functions of IFI6 or the mechanisms for IFI6-mediated effects in pancreatic cancer remain unclear." (PMID 34399768, 2021). "Our study demonstrated that CTD-3252C9.4/IRF1/IFI6 axis may be a novel therapeutic target in pancreatic cancer." (PMID 34399768, 2021). "To elucidate the molecular mechanisms by which CTD-3252C9.4 inhibits IFI6 expression, we first studied the cellular localization of CTD-3252C9.4 in pancreatic cancer cells." (PMID 34399768, 2021). "Here, we firstly verified that IFI6 expression was upregulated and negatively correlated with CTD-3252C9.4 expression in pancreatic cancer cells, tissues, and tumors from mice." (PMID 34399768, 2021). "In both pancreatic cancer cell lines, we found the opposite expression patterns of CTD-3252C9.4 and IFI6." (PMID 34399768, 2021). "Our data indicated that CTD-3252C9.4 could promote pancreatic cancer cell apoptosis and restrain cell growth via binding IRF1 and preventing the transcription of IFI6, which may become a potential therapeutic target for pancreatic cancer." (PMID 34399768, 2021). "Then, IFI6 was identified as a downstream target that could be down-regulated by CTD-3252C9.4 and IFI6 overexpression could counteract the effects of CTD-3252C9.4 upregulation on the survival and apoptosis of pancreatic cancer cells." (PMID 34399768, 2021). "Then, rescue assays indicated that the impaired pancreatic cancer cells growth and facilitating apoptosis triggered by overexpression of CTD-3252C9.4 could be retrieved by up-regulation of IFI6." (PMID 34399768, 2021). "The negative correlation between CTD-3252C9.4 and IFI6 expression levels was further verified in different pancreatic cancer cell lines and PCSCs, CTD-3252C9.4-overexpressing tumors, 20-paired pancreatic cancer tissues and corresponding adjacent normal tissues." (PMID 34399768, 2021).
respiratory infection (2 papers, 2020). "Although the human viral results are ambiguous in action, the pig immune overexpression of IFI6 is consistent across two structurally different respiratory infections in the current study." (PMID 33187194, 2020).
avian diseases (1 paper, 2023). "However, little is known about the role of avian IFI6 in avian diseases; therefore, the structure and function of avian IFI6 are worth exploring." (PMID 38033564, 2023).
Cirrhosis (1 paper, 2023). A chronic disorder of the liver in which liver tissue becomes scarred and is partially replaced by regenerative nodules and fibrotic tissue resulting in loss of liver function. "Macrophage-CD9/IL18 expanded from HBV infection to cirrhosis, while macrophage-CD9/IFI6 expanded from cirrhosis to HCC." (PMID 38116005, 2023).
co-infection (1 paper, 2025). "Co-expression of IFI6, IFITM1 and IFITM3 across lymphoid tissues may be connected to enhanced pathogenesis in co-infection." (PMID 40211134, 2025).
cutaneous melanoma (1 paper, 2023). A primary melanoma arising from atypical melanocytes in the skin. "Among these, IFI6 and IFI44L are associated with the formation and growth of cutaneous melanoma." (PMID 36774490, 2023).
Ebola (1 paper, 2024). "The mechanisms elucidated in these studies, particularly relating to IFI6's antiviral properties and ISG15's role in immune modulation and viral replication inhibition, offer insights that may be relevant in understanding the specific genetic responses we observed in NHPs infected with Ebola." (PMID 39282474, 2024).
esophageal cancer (1 paper, 2024). A primary or metastatic malignant neoplasm involving the esophagus. "The role of the IFI6 gene has been described in several cancers, but its involvement in esophageal cancer (ESCA) remains unclear." (PMID 38473938, 2024).
esophageal carcinoma in situ (1 paper, 2020). "To explore the clinical relevance of IFI6, we assessed the IFI6 abundance in non-cancerous esophageal tissues and in samples with progressively aggressive characteristics: esophageal hyperplasia, esophageal carcinoma in situ, low-grade ESCC, moderate-grade ESCC, and high-grade ESCC using IHC." (PMID 32727517, 2020).
IgA nephropathy (1 paper, 2025). "Recent studies have identified an increased expression of interferon signature genes such as IFI6, IFI44L, and IFITM3 in PBMCs of patients with IgA nephropathy." (PMID 40269956, 2025).
lentivirus infection (1 paper, 2021). Virus diseases caused by the Lentivirus genus. "We used short hairpin RNA targeting two different regions of IFI6 and inserted it into the cell genome by lentivirus infection." (PMID 33868257, 2021).
liver cancer (1 paper, 2023). An epithelial or non-epithelial malignant neoplasm that arises from the liver. "In addition, the overexpression of IFI6 in human liver cancer cells promotes hepatitis C virus replication and weakens the antiviral activity of IFN-α, and the same findings have been observed in liver cancer cells." (PMID 38033564, 2023).
Obesity (1 paper, 2024). Accumulation of substantial excess body fat. "Patients under 65 years old showed a higher expression of TFRC (p = 0.002), CCL5 (p < 0.001) and IFI6 (p = 0.006), and those with obesity (BMI ≥ 30) presented higher expression of OAS1 (p = 0.008) and TGFB1 (p = 0.008)." (PMID 38731851, 2024).
ovarian tumors (1 paper, 2021). "In the current research, prognostic IFI6 is higher in ovarian tumors compared to the normal ovary in mRNA and protein levels." (PMID 34513825, 2021).
polymyositis (1 paper, 2023). A rare idiopathic inflammatory myopathy characterized by symmetric proximal muscle weakness and elevated muscle enzymes. "Another study reported that the breakdown of positive IFN-I signatures (top five IFIGs were IFI6, RSAD2, STAT2, IFI44, and IFI27) in whole blood of patients were 73% SLE, 68% SSc, 66% DM, 61% polymyositis (PM), and 33% RA." (PMID 36979843, 2023).
primary immunodeficiency (1 paper, 2024). "Single-gene enrichment analysis showed that IFI6 and FSCN1 were enriched in the intestinal immune network of the immunoglobulin A production pathway in SSc, whereas IFI6 and FSCN1 were enriched in the primary immunodeficiency signaling pathway in patients with AS." (PMID 39050259, 2024).
renal carcinoma (1 paper, 2018). A carcinoma arising from the epithelium of the renal parenchyma or the renal pelvis. "Small RNA-induced knockdown of GAPDH in renal carcinoma cells was accompanied by increased expression of IFI6, OAS3, and UBE2L6." (PMID 30253781, 2018).
Sepsis (1 paper, 2021). Sepsis is defined as life-threatening organ dysfunction caused by a dysregulated host response to infection. "The deregulation of DEGs including AKT1 (down), IFN-inducible protein 6 (IFI6, down), IL-15 (up), and ANXA1 (up) was verified in the neutrophils from patients with sepsis-induced immunosuppression as compared with controls." (PMID 33761636, 2021).
serous ovarian cancer (1 paper, 2010). "That is, one group including: SSBP1, IFI6 DDT, IFI27, C11orf92, NFKBIA, TNXB, NEAT1 and TFG, was up-regulated in most patients with stage III serous ovarian cancer." (PMID 20969748, 2010).
vitiligo (1 paper, 2022). Generalized well circumscribed patches of leukoderma that are generally distributed over symmetric body locations and is due to autoimmune destruction of melanocytes. "Inflammatory and immune response–related genes such as CD74, IFI27, IFI6, and IFITM1 were also significantly increased, and this was further confirmed by the hallmark pathway enrichment analysis of the genes highly expressed in vitiligo lesional skin using the Molecular Signatures Database (MSigDB)." (PMID 35653192, 2022).
infection (55 papers, 2008 to 2025). The state of being infected such as from the introduction of a foreign agent such as serum, vaccine, antigenic substance or organism. "Another interesting observation from this study is that pH1N1 infection drives upregulation of IFN alpha-inducible protein 6 (IFI6) in major BAL cell subsets." (PMID 39024231, 2024). "Based on the RNA-seq data, IFI6 was the most strongly upregulated gene after either infection (swH1N1: lfc = 2.27, padj = 1.48 x 10-36; huH1N1: lfc = 2.48, padj = 4.43 x 10-44)." (PMID 39247193, 2024). "Primary human Sertoli cells infected with either 5 or 10 MOI of the Zika virus showed a prominent, dose dependant, increase in the expression of ISGs including ISG15, OAS1, IRF1, and IFI6 48 hours post-infection, compared to uninfected controls at 8 hours." (PMID 39621805, 2024). "Four important antiviral ISGs, MX1, MX2, ISG15, and IFI6, were found to be upregulated after infection with either strains of IAV in the lower trachea." (PMID 39247193, 2024). "IFI6's participation in these processes enhances the host's ability to maintain cellular integrity while fighting the infection, illustrating its comprehensive role in viral defense." (PMID 39282474, 2024). "In the present study, it was found that OAS1 and IFI6 were overexpressed in individuals with a high viral load of infection." (PMID 37389217, 2023). "In this work we describe, for the first time, that IFI6 positively affects infection of two highly relevant human respiratory RNA viruses (IAV and SARS-CoV-2)." (PMID 36793726, 2023). "The results of the study increase the understanding of the function of avian IFI6 and provide a theoretical basis for further studies on the pathogenic mechanism of the effects of ARV and for developing specific drugs to fight ARV infection." (PMID 38033564, 2023). "Transduction titers of amphotropic MLV-based vector in HeLa/FAT10, HeLa/IDO1, and HeLa/IFI6 cells were also lower than those in HeLa/empty cells, which shows that FAT10, IDO1, and IFI6 inhibit MLV-based vector infection as well as HIV-1-based vector infection." (PMID 35883685, 2022). "In current study we also detected mRNA expression of IFI6 by qRT-PCR at 48 hrs post-infection in primary HUVECs, and found that IFI6 expression was dramatically increased in infected HUVECs." (PMID 26244642, 2015). "The activation of caspase-3 and intrinsic apoptosis-related protein caspase-9 were down-regulated in IFI6+/+ but up-regulated in IFI6-/- cells at 24–48 hrs post-infection." (PMID 26244642, 2015). "In the present study, the IFN-stimulated genes (IFIT1, IFIT3, MX1, ISG15, OAS1, and IFI6) were dramatically increased at 16 h and 24 h post infection, which should trigger powerful antiviral functions." (PMID 23527143, 2013). "Though, IFI6 expression was higher after infection with huH1N1, especially at the protein level (∼50%), which might contribute substantially to the observed lower antiviral response." (PMID 39247193, 2024). "In addition, we demonstrated increased expression of a protein, IFN alpha-inducible protein 6 (IFI6), 21 days after infection, showing that while immune cells in the lung have common properties, invading organisms can have a long-lasting impact." (PMID 39024231, 2024). "In the IFE cells, infection was associated with the upregulation of interferon regulatory and inducible genes (IRF, IRF9, IFIT5, IFIH1), while a downregulation of IFI35 and IFI6 was observed, potentially indicating a mechanism to prevent excessive immune activation." (PMID 38743760, 2024). "In lower trachea, IFI6 was one of the highest induced antiviral factors at both the protein and RNA level after either infections, indicating an important function in the antiviral immune response regardless of host adaptation level and replication capacity of the infecting strain." (PMID 39247193, 2024). "OAS1 and IFI6 were overexpressed in individuals with a high viral load of infection." (PMID 37389217, 2023).
infection (continued). "Transduction titers on the FAT10-, IDO1-, and IFI6-expressing HeLa cells (HeLa/FAT10, HeLa/IDO1, and HeLa/IFI6 cells) were much lower than those on the control cells, showing that FAT10, IDO1, and IFI6 significantly inhibit amphotropic MLV-pseudotyped HIV-1-based vector infection." (PMID 35883685, 2022). "Furthermore, all identified infection-associated ISG genes (MX1, MX2, OAS1Y/Z, OAS2, ISG15, IFI6, IFI44 and RSAD2) showed lower expression values in Holstein infected cells relative to Sahiwal." (PMID 35061738, 2022). "IFI6 up-regulated in HUVECs after infection with DENV2 for 48 hrs by GeneChip hybridization and analysis (top), and mRNA expression of IFI6 in primary HUVECs isolated from human umbilical veins was markedly up-regulated after 48 hrs post DENV2 infection(below)." (PMID 26244642, 2015). "To further understand the role of IFI6 in apoptosis that was induced by DENV2-mediated infection of VECs, we constructed two stable cell lines of EA.hy926 IFI6+/+ and IFI6-/- cells, which were transfected with IFI6 over-expression (pMSCV-neo-IFI6+) and IFI6 knock-down (pMSCV-neo-IFI6-) plasmids." (PMID 26244642, 2015). "Thus, IFI6 might contribute to suppression of the antiviral immune response after infection with both swH1N1 and huH1N1." (PMID 39247193, 2024). "Therefore, IFI6 may participate in the anti-viral immune process during the infection and replication of SARS-CoV-2, but the specific mechanism still needs to be further studied." (PMID 35928229, 2022). "Among the expression upregulated ISGs, MX, IFIT5, OAS, VIPERIN, ISG12, and IFI6 had the largest expression levels of upregulation (hundreds-fold), and these ISGs all showed a certain pattern of changes: persistent upregulation in the early stage of infection, peaking 3–5 days after infection." (PMID 33614762, 2021). "Thus, the induction of IFI6 in HCV permissive cells may inhibit infection by a number of mechanisms, and inhibition of IFI6 expression during HCV infection may enhance viral persistence and chronicity of infection." (PMID 25757571, 2015). "In contrast, untreated infection networks were dominated by inflammatory mediators (IL6, CXCL10, CCL2, VCAM1, SELE) and antiviral sensors (DDX58, OAS1, IFI44, IFI6), which reflect strong cytokine and interferon-driven immunity." (PMID 41480150, 2025). "IFI27, IFI6, and IFI16 expansion were predicted to initiate a median of 0.27, 0.72 and 0.52 days post-infection, respectively." (PMID 39575237, 2024). "Knockdown of DCAF7 had a relatively minimal effect on suppression of IFI6, IFIT1, OAS1&2 while affecting IFIT2 slightly more with HAdV-B7 infection." (PMID 38940561, 2024). "While the number of significantly upregulated genes decreases to 37, these genes (e.g., ISG15, IFI6, IFI44L, HP, OAS1, IFI44, OASL, and IFI27) likely play a crucial role in the response to the progressing infection." (PMID 39282474, 2024). "The 17 DEGs upregulated after infection with huH1N1 were shared with the swH1N1 infection (DDX58 (RIG-I), RSAD2 (Viperin), MX2, MX1, OAS1, ANGPTL4, IRF7, ISG15, IFIT1, ISG12(A), DDX60, BST2, IFI44, XAF1, LGALS3BP, RTP4, and IFI6)." (PMID 39247193, 2024). "Two mRNAs were down-regulated in all treatment groups at the later time points post-infection, namely, CNTNAP1 and NR4A1, while twenty mRNAs were up-regulated in all later time point treatment groups, including IFI6, LY6E, MX1, OASL, STAT1, and CMPK2." (PMID 38675946, 2024). "In our study, overexpression or inhibition of IFI6 upregulated IRF7 expression and downregulated TBK1, LGP2, IFN-α, and IFN-γ expression after infection with ARV." (PMID 38033564, 2023). "IFI6 was reported to block flavivirus replication, and USP18 was reported to counteract infection by Sendai virus and encephalomyocarditis virus." (PMID 37306574, 2023). "For the gene silencing approach, we utilized siRNA oligonucleotides to specifically reduce expression of IFI6 and IFI27 prior to infection." (PMID 35443155, 2022).
infection (continued). "Both IFI6 and IFI27 transcripts were increased upon infection with P. vivax, however only 23% of the P. vivax positive cells co-expressed the 2 genes." (PMID 35443155, 2022). "To confirm these results, we used real-time quantitative PCR (qPCR) to analyse mRNA levels of the “classical ISGs” Mx1, IFI6 and IFIT5 upon infection with the knockout viruses." (PMID 33352813, 2020). "PKR, IFI6, and OASL overexpression reduced the GFP expression level (and therefore infection) by more than 75% of the control." (PMID 27822537, 2016). "A series of IFN-stimulated and IFN-inducible genes are highly expressed post-infection, and include ISG15, IFI6, IFI44, IFI44L, IRF27, IFIT1, IFIT3, and XAF1." (PMID 26244642, 2015). "These genes contribute to the regulation of iron metabolism (FTH1), modification of proteins in response to infection (HERC5), presentation of antigens to the immune system (MAMU-AG), control of apoptotic pathways (IFI6 and PLAC8), and direct antiviral activities." (PMID 40742121, 2025). "IFI6 regulates by Janus tyrosine kinase (JAK)/ STAT signal transduction pathway and through inhibiting the release of cytochrome c from mitochondria delays apoptosis, which plays a protective role during infection." (PMID 40100809, 2025). "When comparing the models that include infection clearance by the different ISGs, we identified that the per-capita clearance rate of infected cells is a median of 2.5 times faster per IFI27 gene expressed than it is per IFI6 gene expressed (bF1/bF3)." (PMID 39575237, 2024). "Moreover, our study revealed the significant role of genes like IFI6, which, alongside IFI27, showed marked expression level changes in response to the infection." (PMID 39282474, 2024). "IFN-related genes with significant low expression in later infection, such as ISG15 and IFI6, might be involved in creating a permissive environment for late-stage parasite development and replication." (PMID 35443155, 2022). "Overexpression of all the ISGs, except for MAP3K5 and IFI6 whose expression was cytotoxic in HUVEC VP30 cells, significantly reduced EBOV-driven luciferase expression at three days post infection in a similar manner of inhibition to that observed in HEK-293T VP30." (PMID 32528005, 2020). "However, there seemed to be almost no DNA fragments at the early stages of infection in IFI6+/+ cells, which maintained a lower level of apoptosis as compared with the vector-high cells." (PMID 26244642, 2015). "Specifically, suppression of IFI6 and OAS1 was impaired by HAdV-B7 when RuvBL2 was knocked down, but not of IFIT1 nor IFIT2, while only OAS1 expression in HAdV-B14 infection was affected by RuvBL2 knockdown." (PMID 38940561, 2024). "However, the majority of antiviral ISGs, including OAS1, MX2, IFI6, IFITM1, IFI27, and IFTM2, were downregulated in cells transduced with MyD88 (in the presence or absence of infection) and were also downregulated in cells infected with UL88-deficient HCMV vs wild-type HCMV." (PMID 40638072, 2025).